TNF (tumor necrosis factor)
Diseases named in the same sentence as TNF in open-access papers (continued):
Sharing a sentence is not in itself a finding about the gene and the disease.
ovarian carcinoma (295 papers, 1998 to 2026). A malignant neoplasm originating from the surface ovarian epithelium. "For example, elevated concentrations of interleukin-1α (IL-1α), interleukin-8 (IL-8), and tumor necrosis factor-α (TNF-α) are associated with an increased risk of ovarian cancer." (PMID 38881734, 2024). "They demonstrated that CK2 was associated with the TNF network, a network consisting of TNF-α and other cytokines which was released by ovarian cancer cells." (PMID 36530985, 2022). "Numerous cytokines involved in cell-mediated immunity, including IFN-γ, IL-6, MHC, and TNF-α molecules, have been associated with increased growth and patient prognosis in ovarian cancer." (PMID 36386196, 2022). "Tc22 cells (characterised by IL-22, TNF-α, IL-2 production) were associated with a potential improvement with prognostic significance in human ovarian cancer through IL-6 induction." (PMID 35406451, 2022). "C-reactive protein (CRP), interleukin-6 (IL-6), and tumor necrosis factor-alpha (TNF-α) serum markers have shown to be higher in women with malignant ovarian tumors while there is uncertainty if serum levels are associated with unique GI microbes." (PMID 35740687, 2022). "In ovarian cancer, TNFα gene polymorphisms are associated with pathogenesis but remains to be validated." (PMID 33540543, 2021). "Several studies are consistent with our findings and confirm diagnostic relevance of TNF-α in distinguishing malignant ovarian neoplasm from benign masses." (PMID 34573967, 2021). "Accumulation of serum amyloid A (SAA1/2) is associated with inflammation in epithelial ovarian cancer, via the TNF-alpha mediated activation of NF-κB." (PMID 30274280, 2018). "Ovarian cancer is recognized as an inflammation-associated cancer and cancer cells express high levels of tumor necrosis factor-α (TNF) as a potential regulator of the proinflammatory tumor microenvironment." (PMID 27723802, 2016). "We report here that SKOV3 ovarian cancer cells are susceptible to apoptosis induction by C1q via TNF pathway." (PMID 28066412, 2016). "This is intriguing in light of previous studies reporting the presence of TNFα and TGFβ1 in the ascites of the vast majority of ovarian cancer patients and their association with disease progression." (PMID 27659538, 2016). "High expression of this TNFα/MCP-1 signature has been found to be associated with improved 5-year overall survival in ovarian carcinoma patients, suggesting that enhancement of this monocyte and macrophage axis may have significant clinical relevance." (PMID 33081206, 2020). "In conclusion, we have identified kinases, particularly CK2, associated with the TNF network that may play a central role in sustaining the cytokine network and/or mediating its effects in ovarian cancer." (PMID 26871292, 2016). "Furthermore, elevated level of serum cytokines IL-2, IL-5, IL-6, IL-10, and TNF-α in ovarian cancer patients, might be associated with ovarian cancer progression." (PMID 37322531, 2023). "This autocrine inflammatory cytokine network was characterized in ovarian cancer cell and macrophage co‐culture models and further validated in vivo using TNF‐α knockout mice and antibody blockade approaches." (PMID 40968783, 2026). "Tumor necrosis factor (TNF) is required in inflammation and apoptosis in the ovarian cancer microenvironment." (PMID 40968783, 2026). "In ovarian cancer, TNF constitutes a malignant cell‐autonomous inflammatory cytokine network, contributing to tumor cell proliferation, invasion, and drug resistance, particularly through the interactions between tumor cells and macrophages." (PMID 40968783, 2026). "PTE has the potential to treat ovarian cancer by reducing the level of TNF-a cytokine via inhibition of AKT- and ERK-mediated pathways in the human ovarian cancer cell line, IGROV-1 cells." (PMID 40564264, 2025). "It has been demonstrated that overexpression of MAP3K3 plays a role in regulating NF-κB signaling through TNF in ovarian carcinoma." (PMID 41190326, 2025).
ovarian carcinoma (continued). "M2 macrophages, characterized by high levels of anti-inflammatory markers such as IL-10 and reduced pro-inflammatory factors like TNF-α, contribute to the immune suppression, tumor progression, and metastasis commonly seen in ovarian cancer." (PMID 40330466, 2025). "M1 macrophages release pro-inflammatory cytokines, particularly TNF-α, which triggers the nuclear translocation of NF-κB subunits (p50, p65) from the cytosol to the nucleus in ovarian cancer cells." (PMID 40330466, 2025). "A recent study demonstrated that PARP inhibitors induce pyroptosis in ovarian cancer via a TNF–caspase-8–GSDMD/E axis, generating immunogenic cell death that remodels the tumor immune microenvironment and expands T cells specific for tumor-derived neoantigens." (PMID 41291696, 2025). "IL-6 demonstrated strong diagnostic and prognostic potential, reaching an AUC of 1.000 in ovarian cancer when used alone or with VEGF-A and was associated with poorer survival when elevated alongside TNF-α." (PMID 41010973, 2025). "Cytokines such as tumor necrosis factor alpha (TNF-α) and interleukin-6 (IL-6) have been reported in subjects with many severe diseases, such as cervical carcinoma and ovarian cancer." (PMID 40136934, 2025). "Mesenteric fat secretes adipokines and cytokines such as leptin, adiponectin, TNF-α, and IL-6, creating a pro-inflammatory environment that drives ovarian cancer cell proliferation and migration." (PMID 39285292, 2024). "In a mouse model of ovarian cancer, TNF-α was found to stimulate the secretion of other cytokines, such as IL-17, by CD4+ T cells and indirectly promote tumor growth." (PMID 38644421, 2024). "TNF is widely expressed in ovarian cancer and studies show levels of TNFα are elevated in malignant ovarian tissues, serum and ascites." (PMID 39621651, 2024). "Mechanistically, suppressing NF-κB signaling in ovarian cancer cells changed the effect of TNFα signaling from promoting proliferation to inducing cell death." (PMID 38877579, 2024). "According to a recent study, patients with recurrent ovarian cancer exhibit increased levels of interleukin-6 and TNF-α in serum compared with levels in patients with NR ovarian cancer." (PMID 39135097, 2024). "One study investigated the effects of caspase 8 depletion on apoptosis and necroptosis of TNFα-stimulated ovarian cancer cells." (PMID 38877579, 2024). "This suggests that ovarian cancer has a direct effect on the kidney’s function, as the tumor led to increase in expression levels of IL-1β, TNFα, IL6, and GDF-15." (PMID 39394174, 2024). "TNF-α stimulates CA-125 in breast, endometrial, and ovarian cancers through nuclear factor kappa B (NF-κB)." (PMID 39669673, 2024). "IL-6, IL-10, TNF-α, IFN-γ, TNF-α have been substantiated as directly linked to poor outcomes in epithelial ovarian cancer (EOC) patients." (PMID 38279997, 2024). "investigate the role of TNF alpha in the advancement of ovarian cancer, encompassing serous and clear cell subtypes, and observe heightened expression levels of TNF alpha in comparison to normal ovarian tissue." (PMID 38384812, 2024). "TNF-α levels are elevated in ovarian cancer and depend on the upregulation of TNF-α expression by TNF-α." (PMID 37108425, 2023). "Significantly reduced expression of NKG2D, high level of MICA as well as IL-6, IL10 and TNF-α indicates immune suppression of ovarian cancer patients.." (PMID 37322531, 2023). "It is reported that tumor necrosis factor played an important role in apoptosis in an ovarian cancer cell line." (PMID 36673375, 2023). "The area under the receiver operating curve and the sensitivity of serum TNF‐α in predicting ovarian cancer recurrence were higher than those of IL‐6 and IFN‐γ." (PMID 37904699, 2023). "After adjusting for confounding factors, the results showed that the serum IL‐6, IFN‐γ, and TNF‐α levels were influencing factors of recurrence in epithelial ovarian cancer patients." (PMID 37904699, 2023).
ovarian carcinoma (continued). "Our results show that the specificity of serum TNF‐α in predicting recurrence in ovarian cancer patients and the area under the ROC curve are higher than IL‐6 and IFN‐γ." (PMID 37904699, 2023). "The production results from local pro-inflammatory cytokine responses, such as TNF-α, expressed mainly in ovarian cancer." (PMID 37792745, 2023). "In conclusion, our study found that the increased IL‐6 and TNF‐α levels in recurrent ovarian cancer patients, while the decreased IFN‐γ level, the CD4+ T‐cell proportion, and the CD4+/CD8+ ratio." (PMID 37904699, 2023). "Relatedly, anti-inflammatory evidence of withaferin A has been shown in ovarian cancer cells by suppressing the secretion levels of various pro-inflammatory cytokines, such as tumor necrosis factor-alpha (TNFα), IL-6, IL-8, and IL-18 in ovarian cancer cells." (PMID 37110423, 2023). "Logistic regression equation analysis suggests that serum TNF‐α is the influencing factors for patient recurrence, and the ROC curve shows that serum TNF‐α levels have a certain diagnostic effect (AUC = 0.802) on ovarian cancer recurrence." (PMID 37904699, 2023). "ADAM17 promotes the malignant progression of ovarian cancer and causes chemo-resistance by mediating ADAM17-dependent shedding of AREG, HB-EGF, IL-6Rα, TNF, TNFR1-α, TGFα and activating the EGFR signaling pathway." (PMID 36466812, 2022). "We examined the effects of hepatocyte growth factor (HGF), epidermal growth factor (EGF), and tumor necrosis factor alpha (TNFα), which are particularly relevant to the progression of ovarian cancer." (PMID 35676254, 2022). "Wogonin inhibited the proliferation of ovarian cancer cells by activating apoptosis and cell cycle arrest, and it also increased tumor necrosis factor (TNF-α) and promoted the apoptosis of liver cancer cells." (PMID 36415861, 2022). "CD44 expression in ovarian cancer cells is crucial in binding hyaluronan, and TNFα, which is secreted by adipocytes, has been reported to induce the expression of CD44 in ovarian cancer cells through activation of JNK." (PMID 35565396, 2022). "In patients with platinum-resistant ovarian cancer, however, targeting a specific cytokine/chemokine (e.g., monoclonal antibodies against IL-6 or TNF-α) has only shown a transient and limited antitumor effect." (PMID 36386196, 2022). "It was shown in vitro that the levels of TNF-α and IL-6 mRNA were 1000-fold higher in ovarian cancer cells than in normal ovarian epithelial cells." (PMID 35453670, 2022). "A recent study showed that LPA induces secretion of TNF-alpha in ovarian cancer cells and thus, adjusts an inflammatory network in ovarian cancer." (PMID 35365723, 2022). "Tumor necrosis factor was fused to cCpE and shown to be efficiently delivered and more cytotoxic to ovarian cancer cells than un-fused tumor necrosis factor." (PMID 35269525, 2022). "A2780, SK-OV-3, OVISE, OVCAR-8, Hey cells were taken from different parts of ovarian cancer patients, and their tolerance to tumor necrosis factor and several cytotoxic drugs, including cisplatin and doxorubicin, was different." (PMID 35268616, 2022). "Mechanistically, treatment with CHIR99021 leads to an increased production of proinflammatory cytokines (IFN-γ, tumor necrosis factor α (TNFα)) and upregulates NK cytotoxicity against ovarian cancer cells." (PMID 35681507, 2022). "It stimulates the production of TNF-α and interleukins IL-6 and IL-12 in adipocytes as well as in immune system cells involved in the pathogenesis of ovarian cancer." (PMID 35453670, 2022).
ovarian carcinoma (continued). "According to ATCC, it is resistant to cytotoxic chemicals, including diphtheria toxin and tumor necrosis factor, as well as, therapeutic anti-ovarian cancer medicines like cis-platinum and Adriamycin." (PMID 35965557, 2022). "These antibodies have been called “dominant” antagonistic antibodies due to their ability to diminish human ovarian cancer cells in the ascites and cutaneous T cell lymphoma, even under TNF induction." (PMID 35741080, 2022). "A recombinant fragment of human SP-D (rfhSP-D) decreases the motility and proliferation of ovarian cancer cells by inhibiting the mammalian target of rapamycin (mTOR) activity, increasing caspase 3 cleavage, and inducing pro-apoptotic genes Fas and TNF-α." (PMID 36077500, 2022). "TNF-α and IL-1β induced SPATA2 expression in ovarian cancer cells and that increased SPATA2 expression was associated with poor prognosis of ovarian cancer patients." (PMID 35754839, 2022). "It was reported that pancreatic and ovarian cancer cells with overexpression of ST6Gal-I exhibited resistance to TNF-induced apoptosis and reduced caspase-8/3 activation upon extended TNF treatment." (PMID 34577144, 2021). "Etanercept, a recombinant TNF receptor that binds to TNF- α and inactivates it, has shown therapeutic efficacy in recurrent ovarian cancer patients." (PMID 34912809, 2021). "TNF- α is a major cytokine constitutively expressed in most malignant ovarian carcinomas and is responsible for cell proliferation, invasion, stemness by secreting cytokines, angiogenic factors, and MMPs." (PMID 34912809, 2021). "For example, the PARPi talazoparib significantly increased the number of peritoneal CD8 T cells as well as their production of interferon-γ (IFN-γ) and TNF-α in a mouse model of ovarian cancer." (PMID 34885119, 2021). "Additional studies with a larger sample of patients are needed to confirm the role of IL-6 in ovarian cancer diagnostics as well as further evaluate the clinical importance of IL-8 and TNF-α in patients with ovarian carcinoma and benign cystic lesions." (PMID 34573967, 2021). "Caspase 8 is involved in this complex mechanism mediating pro-survival NFκB signaling or triggering extrinsic apoptosis downstream of short-term stimulation with TNFα in ovarian cancer cells." (PMID 34088893, 2021). "We previously demonstrated that NFκB inhibition can induce cell death by apoptosis in ovarian cancer cells dependent on a TNFα-induced pathway for proliferation." (PMID 34088893, 2021). "The cutoff values for the interleukin 6, interleukin 8, and TNF-α that were elevated in patients with ovarian carcinoma (OC Group) were calculated using ROC curve analysis." (PMID 34573967, 2021). "Studies have shown that interleukin-22 is an important factor in the ovarian cancer tumor microenvironment because it stimulates tumor growth by increasing proliferation and serves as a protective factor for ovarian cancer during TNF-induced apoptosis." (PMID 34300224, 2021). "Of note, treatment with the PARPi talazoparib significantly increased the number of peritoneal NK cells as well as their production of IFN-γ and TNF-α in a mouse model of ovarian cancer." (PMID 34885119, 2021). "In our study, we found a positive correlation between the occurrence of ovarian cancer and the level of IL-8 and TNF-α in patient’s serum." (PMID 34573967, 2021). "De novo expression of transforming growth factor-alpha (TGFa) is induced in omental stromal fibroblasts whereas tumor necrosis factor-alpha (TNFa) is expressed by ovarian cancer cells." (PMID 34206026, 2021). "The expression of CXCR6 in ovarian cancer tissues is higher than that in adjacent tissues and is positively correlated with the expression of TNF-α." (PMID 33829065, 2021). "The presented study results, as well as reports from other authors indicate that IL-8 and TNF-α can be used as biomolecular markers to provide clues for distinguishing ovarian cancer from benign cystic lesions." (PMID 34573967, 2021).